MMP2 (matrix metallopeptidase 2)
Diseases named in the same sentence as MMP2 in open-access papers (continued):
Sharing a sentence is not in itself a finding about the gene and the disease.
Obesity (continued). "Current studies have shown higher levels of MMP-2 and MMP-9 in patients with obesity, metabolic syndrome, and T2DM compared to control groups." (PMID 39766340, 2024). "Metalloproteinases, particularly MMP2, MMP9, and MMP19, regulate the extracellular matrix, which is crucial in multifactorial conditions like obesity and related diseases." (PMID 39683581, 2024). "For instance, leptin secreted by adipose stromal/stem cells isolated from women with obesity enhances the expression of epithelial-to-mesenchymal transition (EMT) and metastasis-related genes, such as serpine 1, matrix metalloproteinase 2 (MMP-2) and IL-6." (PMID 36670988, 2023). "Increased levels of MMP-2 and MMP-9 in subjects with obesity and type 2 diabetes, as well as obesity-related insulin resistance have been demonstrated in several studies." (PMID 37697354, 2023). "MMP-2 and MMP9 are the subclasses of metalloproteases involved in the development of obesity and insulin resistance, and indeed MMP-9 plasma levels are higher, despite lower protein levels in SM under HFD (60% fat) fed C57BL/6J mice." (PMID 33803198, 2021). "The enrichment analyses highlighted the interaction between TIMP2 and MMP2 genes and the molecular pathways involving the ECM remodeling in the obesity condition." (PMID 34722599, 2021). "In the context of obesity and inflammation, elevated MMP2 expression and MMP9 activity are found in a mouse model of obesity and positively correlated with inflammatory cytokine expression." (PMID 34745017, 2021). "In obesity, MMP expression is modulated in adipose tissue and MMPs (e.g., MMP-2 and MMP-9) potentially affect adipocyte differentiation." (PMID 26599360, 2015). "MMP2 and MMP9 exert a pivotal role in adipose tissue remodeling that occurs during the development of obesity." (PMID 24871103, 2014). "Similarly, circulating levels of MMP-2 (72 kDa type IV collagenase), a key metalloproteinase involved in the removal of excess ECM, are higher in people with obesity than in lean people." (PMID 40171198, 2025). "Accordingly, we want to assess the profile of MMPs and TIMPs gene expression (MMP-2, 9, 12, 14, TIMP-1,2) in peripheral leukocytes, and plasma levels of MMP-2, 9, TIMP-1,2 of children with simple obesity to find out if they correlate with obese-related parameters." (PMID 38541059, 2024). "Adipocytes contribute to the secretion of proinflammatory cytokines such as TNF-α, IL-1β, MMP-2, MMP-9, IL-6, and MCP-1, as well as adipokines like adiponectin, which further contribute to chronic inflammation in adipose tissue of individuals with obesity." (PMID 38495901, 2024). "This study aims to determine plasma concentrations of MMP-2 and MMP-9, as well as clinical and laboratory parameters related to obesity throughout the follow-up period, to investigate the associations between these markers and the effects of weight loss in patients undergoing bariatric surgery." (PMID 39766340, 2024). "In another study, evaluating MMP levels in obesity revealed that in obese individuals, the level of MMP-2 is higher compared to overweight or non-obese individuals." (PMID 38612961, 2024). "This study sought to determine the responses in circulating APN, MMP-2, MMP-3 and OPN—key proteins involved in the remodelling of adipose tissue —following two different exercise formats in individuals with overweight or obesity." (PMID 36648516, 2023). "Active ingredients in WP, such as oxidized glutathione, may improve symptoms of HFD-induced obesity by acting on targets such as EGFR, NOS3, MMP2, PLG, PTGS2, and AR." (PMID 38162665, 2023). "Increased plasma concentrations of MMP-2 and MMP-9 were found in patients with obesity and T2D." (PMID 37446346, 2023). "Although the balance between TIMP2 and MMP2 seemed essential for ECM remodeling, we demonstrated that decreased TIMP2 expression in PBMC could be a marker of improvement of obesity after 6 months of RYGB." (PMID 34722599, 2021).
Obesity (continued). "Although mRNA levels of MMP2 were higher in patients with obesity, differences were not statistically significant (p = 0.078)." (PMID 32283761, 2020). "High MMP-2 and MMP-9 activity may be related to immunity, tumor progression or apoptosis, rheumatoid arthritis, obesity and may play a role in cardiovascular disease diagnoses." (PMID 29593554, 2018). "Notably, MMP2 has been reported to be high in the SAN head region compared to the atrial tissue and decreases with age and obesity." (PMID 28934329, 2017). "Descriptive statistics of all study participant serum samples tested for Bone Panel (osteoprotegrin (OPG), leptin, parathyroid hormone (PTH) and insulin), Matrix Metalloproteinase Panel (MMP-2, MMP-8, MMP-9) and Obesity Panel (adiponectin and C-reactive protein (CRP))." (PMID 23577067, 2013). "Descriptive statistics of all study participant saliva samples tested for Bone Panel (osteoprotegrin (OPG), leptin, parathyroid hormone (PTH) and insulin), Matrix Metalloproteinase Panel (MMP-2, MMP-8, MMP-9) and Obesity Panel (adiponectin and C-reactive protein (CRP))." (PMID 23577067, 2013). "Notably, IL-6, IL-8, AEA, OEA, MMP-2, and TNF-α were elevated in individuals with MUO and also correlated positively with BMI, further reinforcing the link between chronic inflammation and obesity." (PMID 40153192, 2025). "In addition to MMP2, our laboratory has demonstrated that MMP14 cleaves the catalytic domain of MMP11, an important regulator of energy metabolism protecting from diet-induced obesity, fatty liver and insulin resistance." (PMID 37445827, 2023). "However, in two animal models of genetic obesity (ob/ob and db/db) and in a HFD model, while mRNA levels for MMP2, MMP3, MMP12, MMP14, MMP19, and TIMP1 are robustly induced, MMP7 (and MMP3) transcripts are markedly reduced in obese visceral adipose tissue compared to lean tissue." (PMID 37445827, 2023). "The present study demonstrated the modifying effect of obesity on the association of MMP gene polymorphisms with BC: rs17576, and rs2250889 MMP9 were BC protective factors in obese women; rs243865 MMP2, and rs3787268 MMP9 determined BC susceptibility in non-obese women." (PMID 36289879, 2022). "However, in the same work, Beales and colleagues demonstrated that adiponectin was able to antagonize leptin effects observed in EAC malignant cells, including MMP-2 and MMP-9 downregulation, thus indicating the importance of hormonal imbalance induced by obesity during EAC genesis and progression." (PMID 32079295, 2020). "Subdividing people with obesity into MetsO and MHO, a negative correlation was also detected between MMP-2 levels, MMP-2/TIMP-2 ratio and CRP values in MetsO (r = − 0.26, p = 0.03, r = − 0.27, p = 0.03, respectively)." (PMID 34625635, 2021). "On the other hand, these approaches accentuated the role of the MMP2 gene at the FTO locus in skeletal myotubes, given its consistency within the GnRH signaling pathway, which is in line with previous studies linking its expression with obesity." (PMID 39813287, 2025). "In addition, mice lacking MMP-2, but not MMP9, are also resistant to obesity induced by high-fat diet." (PMID 31627295, 2019).
ischemic stroke (66 papers, 2006 to 2025). A stroke disorder caused by obstruction of blood flow to the brain, due to thrombotic (local blood clot formation) or embolic (due to a blood clot or other material traveling from another site) event. "IL1B gene polymorphisms affect the risk of MI and ischemic stroke in young adults by modulating the expression of NF‐κB, iNOS, MMP‐2, and Bax." (PMID 38526027, 2024). "We report that MMP-2 levels were decreased in the brain tissue and plasma of our choline-deficient-diet male offspring following ischemic stroke, whereas MMP-9 levels were unaffected in the treatment groups." (PMID 39273042, 2024). "We report reduced levels of MMP-2 in the brain and plasma tissue of male offspring 1.5 months after undergoing induced ischemic stroke from mothers deficient in choline." (PMID 39273042, 2024). "Tissue inhibitor of metalloproteinase 2 (TIMP2) is a crucial endogenous inhibitor of matrix metalloproteinase-2 (MMP-2), and its expression changes are associated with the development of ischemic stroke and intracerebral hemorrhage." (PMID 37178321, 2023). "Four additional MMP-2 SNPs were nominally associated with ischemic stroke outcome at three months (0.0162<P < 0.0412)." (PMID 20222942, 2010). "Interestingly, our results show that male offspring from maternal mice with choline-deficient diets had decreased MMP-2 levels present in their plasma and brain tissue following ischemic stroke." (PMID 39273042, 2024). "MMP-2 elevations, at least in the acute phase of ischemic stroke, might also be associated with better clinical outcomes." (PMID 28936196, 2017). "Four and a half weeks after ischemic stroke, we measured the levels of MMP-2 and MMP-9 in plasma isolated from female and male offspring from mothers maintained on the CD, ChDD, or FADD prior to and during pregnancy and lactation." (PMID 39273042, 2024). "No previous reports have clearly compared the time-dependent expression of different MMPs (MMP-9, MMP-3, MMP-2) after r-tPA treatment in ischemic stroke and their presence in neuronal or vascular compartments." (PMID 39273389, 2024). "Our findings indicate that in experimental ischemic stroke with reperfusion, the duration of ischemia and r-tPA treatment significantly impacts the expression of MMP-2, MMP-3, and MMP-9, as well as the extent of ischemic brain injury and neurological outcomes." (PMID 39273389, 2024). "A study conducted over a sample size of 556 participants (298 with ischemic stroke versus 258 control) successfully showcased a lower concentration of MMP-2 methylation level in peripheral blood exclusively in male small-vessel occlusion participants." (PMID 36312038, 2022). "The patients suffer from the ischemic stroke exhibit the enhance level of MMP (MMP-2 and MMP-9) in the circulation." (PMID 34795593, 2021). "From this family, two specific variants, MMP-2 and MMP-9, emerge as having a direct link to ischemic stroke." (PMID 34445740, 2021). "One study showed that the MMP-2-735C allele and the MMP-9-1562T allele are independent risk factors that increase the risk of ischemic stroke 1.5 fold compared to other genotypes." (PMID 34445740, 2021). "In an experimental ischemic stroke and traumatic brain injury, the inhibition of MMP-2 and MMP-9 reduced BBB damage and improved the outcomes." (PMID 34834200, 2021). "The interactions between RAGE and MAPK during ischemic stroke promoted the expression of MMP-2 and MMP-9." (PMID 33584203, 2020). "A study reported that MMP-2-mediated degradation of occludin contributes to blood-brain barrier damage in early ischemic stroke." (PMID 33076507, 2020). "In contrast, the MMP-2 protein level has been observed to increase several days after ischemic stroke, when barrier leakage is presumably restored, and formation of glial scarring begins." (PMID 32796743, 2020). "Treatment with LSZ significantly alleviated BBB damage induced by ischemic stroke, which was accompanied by the downregulation of MMP-2/9, VEGF, and HIF-1α." (PMID 32215051, 2020).
ischemic stroke (continued). "We demonstrated TGF-019 has sufficient sensitivity for the specific MMPs suspected in evoking HT during ischemic stroke, i.e., MMP2, MMP9, and MMP3." (PMID 30723388, 2019). "We detected a significant post-ischemic stroke increase in MMP2 mRNA expression in EcoHIV infected brains as compared to mock-infected mice, an effect that was significantly abrogated in ART-11 (but not in ART-7) treated mice." (PMID 31043599, 2019). "They show that patients suffering from ischemic stroke have lower levels of MMP2 methylation at multiple CpGs as compared to healthy controls." (PMID 29792221, 2018). "Yet, MMP-2 activity increases in the later phase of ischemic stroke and basal MMP-2 levels were higher in patients with stable or recovering symptoms." (PMID 28936196, 2017). "Among MMP family members, gelatinases MMP-2 and 9 have been a research focus in ischemic stroke because of their substrate specificity for fibronectin, laminin, collagen type IV and tight junction proteins, which are structural components of the BBB." (PMID 22146586, 2011). "VNS reduced BBB disruption in a rat model of ischemic stroke, protected tight junction proteins from microvascular damage, and reduced the expression of matrix metalloproteinase-2/9 (MMP-2/9) in activated perivascular astrocytes surrounding the damaged vessels." (PMID 39996843, 2025). "Additionally, ischemic stroke triggers MMP activity, notably MMP-2 and MMP-9, implicated in BBB disruption and extracellular matrix degradation." (PMID 38872149, 2024). "MMP‐2/9 are gelatinases that play the most important roles in ischemic stroke." (PMID 37452512, 2023). "Previous preclinical and clinical studies have shown promising results, suggesting that MMP-9 and MMP-2 may predict ischemic stroke outcomes, including hemorrhagic transformation (HT) and cerebral infarction volume." (PMID 37675160, 2023). "Plasma MMP‐2 levels increase after the onset of ischemic stroke, especially lacunar stroke." (PMID 37452512, 2023). "MMP‐2/9 levels increase at different time points after ischemic stroke." (PMID 37452512, 2023). "Using PyMOL software, Discovery studio 4.5 client, and Autodock tools 1.5.6 software, the interaction between potential active compounds (Tanshinol A, Tanshinol B, Tanshinone II A and Przewaquinone C) and ischemic stroke related proteins (MMP2, STAT3, TERT, and ESR1) was studied." (PMID 36133785, 2022). "Relationship between rs14070 of MMP2 and ischemic stroke in different subgroups." (PMID 35959401, 2022). "Thus, narrowing the use of MMP-2 serum concentration as an effective marker in post-ischemic stroke." (PMID 36312038, 2022). "Relationship between rs243849 of MMP2 and ischemic stroke in different subgroups." (PMID 35959401, 2022). "Since the MMP2 inhibitor TIMP2 blocked oxidative stress-induced apoptosis in a mouse model of ischemic stroke, and showed high endogenous levels in primary hucMSCs in our work, we hypothesized its cardioprotective effect in MI injury." (PMID 31182988, 2019). "However, the knowledge about the interaction between tPA and MMP2 and 9 after ischemic stroke remains quite limit." (PMID 26881424, 2016). "MMP-2/9 is mainly produced by injury stimulators such as inflammatory cytokines, serine proteinases, transcriptional factors, and free radicals during reperfusion in ischemic stroke." (PMID 25815722, 2015). "pGSN is cleaved in vitro by MMP-3, MMP-2, MMP-1, MMP-14 and MMP-9 which may be the cause of the severe depletion of pGSN observed in patients who suffer ischemic stroke." (PMID 22047744, 2011). "In this study, we focused on MMP-2, which has been reported to play an important role in the pathogenesis of BBB disruption in many neurological diseases, such as epilepsy, ischemic stroke, and dementia." (PMID 37889501, 2023). "The aim of our research was to analyze non-specific laboratory data, including admission laboratory parameters, as well as baseline levels of MMP-2 and MMP-9 in the serum of patients with ischemic stroke." (PMID 37675160, 2023).
ischemic stroke (continued). "Examination of the activity of MMP-2 and MMP-9 in protein extracts from human brain tissue at different time points after ischemic stroke revealed a transient dependence during the course of pathology." (PMID 37511788, 2023). "Previous studies documented that MMP-2 and MMP-9 are essential in BBB disruption during ischemic stroke." (PMID 37955765, 2023). "In RT-PCR assays, mRNA levels of TNF-α, IL-1β, MMP-2, and MMP-9 were remarkably elevated following ischemic stroke." (PMID 36186136, 2022). "Evidence of this was confirmed in vivo-studies that showed that MMP-2 and MMP-9 levels, intima-media thickness, and the stability of the plaques are strongly correlated with the ischemic stroke process." (PMID 34445740, 2021). "Gelatin zymography showed that both MMP-2 and MMP-9 activities were significantly increased in the ipsilateral hemisphere following ischemic stroke." (PMID 34299128, 2021). "Activities of matrix metalloproteinase-2 and -9 (MMP-2 and MMP-9) significantly increased during ischemic stroke in both animal models and patients." (PMID 34299128, 2021). "Together, genetic deletion of IRAK-M accentuated BBB disruption via the upregulated expression of MMP-2 and MMP-9 in the mouse model of ischemic stroke." (PMID 30622459, 2018). "Although different types of MMPs act differently, there is accumulating evidence that MMP-2, MMP-9, and MMP-12 are involved in the pathogenesis of BBB disruption and cerebral edema formation during ischemic stroke." (PMID 30131754, 2018). "Actually, MMP-2 activity has been shown increased in the latter phase of in ischemic mice model and the MMP-2 levels are higher in ischemic stroke patients in the recovery phase." (PMID 30131754, 2018). "MMP-2 and MMP-9 released from the vascular endothelium and leukocytes during the inflammatory phase of ischemic stroke use collagen IV and laminin as substrates." (PMID 25280484, 2014). "We determined the effect of hNSCs on MMP-9 and MMP-2, proteins that participate in BBB breakdown following ischemic stroke." (PMID 25418536, 2014). "Evidence suggests that MMP-2 and MMP-9 play different roles in BBB disruption during ischemic stroke." (PMID 23565108, 2013). "Matrix metalloproteinases 2 and 9 (MMP-2 and MMP-9) are increased in the brain after experimental ischemic stroke in rats." (PMID 16846501, 2006). "Studies have shown that in the early stage of ischemic stroke, the activity of MMP-2 was not significantly up-regulated." (PMID 38927572, 2024). "MMP2, MMP3 and MMP9 are critical MMPs involved in BBB opening after ischemic stroke." (PMID 37611902, 2024). "However, there is controversy regarding the role of MMP-2 and MMP-3 after r-tPA treatment in ischemic stroke." (PMID 39273389, 2024). "MMP-2 has been reported to regulate TJPs, basement membrane proteins, and PECAM-1 as substrates and is involved in BBB breakdown via disruption of TJPs in several neurological diseases such as epilepsy and ischemic stroke." (PMID 37889501, 2023). "It was found that MMP-2 is the initiator of BBB derangement following cerebral ischemia, while MMP-9 is the principal contributor to BBB dysregulation in the delayed phase after ischemic stroke." (PMID 37955765, 2023). "Matrix-metalloproteinase-2 and -9 (MMP-2 and MMP-9) are upregulated during ischemic stroke." (PMID 36986541, 2023). "For further verification, potential core targets (STAT3, MMP2, ESR1, TERT, and MMP9 proteins) for ischemic stroke and core active ingredients (Tanshinol A, Tanshinol B, Tanshinone II A, and Przewaquinone C) for Salvia miltiorrhiza Bge. were further verified by molecular docking." (PMID 36133785, 2022). "Furthermore, the upregulation of ET-1 promoted the expression of MMP2 and downregulated that of the inter endothelial TJ OCLN after an ischemic stroke." (PMID 34834200, 2021). "The actions and phases of MMP-2 and MMP-9 differ in the case of an ischemic stroke." (PMID 34299128, 2021).